MCM2 (minichromosome maintenance complex component 2)
Diseases named in the same sentence as MCM2 in open-access papers (continued):
Sharing a sentence is not in itself a finding about the gene and the disease.
prostate carcinoma (17 papers, 2005 to 2025). A carcinoma that arises from epithelial cells of the prostate gland. "Here, we report that MCM2, MCM3, MCM4, and MCM6 (MCM2/3/4/6) are elevated in human NEPC and high levels of MCM2/3/4/6 are associated with liver metastasis and poor survival in prostate cancer patients." (PMID 34172788, 2021). "Elevated CDC7 and MCM helicase expression levels in these cell models, especially the CDC7 direct target MCM2 subunit, correlate with higher proliferative rates observed in clinical prostate cancer with disease progression." (PMID 41413594, 2025). "miRNA-1296 targets MCM2 mRNA in prostate cancer cells and over expression of miRNA-1296 results in a significant decrease in MCM2 mRNA, protein, and S-phase of the cell cycle." (PMID 31787077, 2019). "Moreover, it inhibited the invasion of prostate cancer cells and lowered the expression of MCM2/MCM3, PCNA, and CDK2." (PMID 37682177, 2023). "Regulation of MCM2 protein expression by miR-31 was recently reported in prostate cancer." (PMID 25098679, 2014). "Furthermore, MCM2 expression correlated with prostate cancer progression, whereby reduced expression of miR-1296 was observed in prostate carcinoma compared to benign prostate hyperplasia." (PMID 25254214, 2014). "In human prostate carcinoma PC3 cells, knockdown of miR-1296 increases both minichromosome maintenance 2 (MCM2) mRNA and protein." (PMID 29089858, 2017). "miR-31 has a known role in prostate cancer and melanoma, suppressing key cell cycle regulators and pro-oncogenic genes such as CDK1, E2F2, EXO1, FOXM1, MCM2, Src or MET." (PMID 25644061, 2015). "Trichostatin A (TSA), a classical histone deacetylase inhibitor, and genistein, a nontoxic dietary isoflavone isolated from Genista tinctoria, inhibited the expression of MCM2 and MCM2-7 loading factors, such as cyclin-dependent kinase 2 (CDK2), in prostate cancer." (PMID 35880481, 2022). "p‐STAT3, Mcm2, and/or MSR1 were selected out of 10 biomarkers to construct a biomarker index for predicting cancer and high‐grade prostate cancer (HGPCa) in the training cohort based on the stepwise logistic regression analysis; these biomarkers were then validated in the validation cohort." (PMID 32860339, 2020). "While in prostate cancer PC3 cells of human beings, the low expression of miR-1296 can upregulate both minichromosome maintenance 2 (MCM2) mRNA and protein, and conversely, its overexpression can lower the level of the both and even shorten the S phase of the cell cycle." (PMID 28099468, 2017).
colorectal cancer (15 papers, 2013 to 2025). A primary or metastatic malignant neoplasm that affects the colon or rectum. "We found the top-10 gene that was co-mutated with MCM2, which have been reported in multiple cancers, such as colorectal cancer, BRCA, LUAD and LIHC." (PMID 35693940, 2022). "MCM2 expression was reported to be associated with colorectal cancer stage and prognosis and used to detect colorectal cancer in stool." (PMID 29651323, 2018). "In colorectal tumors MCM2 expression significantly associated with histological grade, Dukes' stage, and existence of metastases, therefore it could become an indicator for the management of colorectal cancer patients." (PMID 28161520, 2017). "This explanation was related to a better prognosis in colorectal cancer with higher MCM-2 expression." (PMID 34272446, 2021). "MCM2 is also highly expressed in colorectal cancer and is positively correlated with lymph node metastasis, depth of invasion and Dukes staging." (PMID 34993142, 2021). "Real-time PCR showed that MCM2, RNASEH2A, and TOP2A were upregulated in colorectal cancer compared with adjacent mucosa samples (MCM2, P < 0.001; RNASEH2A, P < 0.001; TOP2A, P = 0.001)." (PMID 29651323, 2018). "Briefly, one cell proliferation marker, Ki-67 antigen (Ki-67), was upregulated in the cells with overexpressed GAS2, “Correlation between proliferation markers: PCNA, Ki-67, MCM-2 and antiapoptotic protein Bcl-2 in colorectal cancer”." (PMID 27284567, 2016). "In colorectal cancer Mcm2 was shown to be a stronger indicator of proliferative cells than Ki67/MIB-1." (PMID 23618321, 2013). "Expression of hepatocyte Mcm-2, cyclin A, PH3 and p21 were negligible in normal liver tissue (<0.01% of hepatocytes in the background liver with colorectal cancer metastasis)." (PMID 24086266, 2013). "Our study confirmed that MCM2, RNASEH2A, and TOP2A were upregulated in colorectal cancer." (PMID 29651323, 2018).
lung adenocarcinoma (12 papers, 2006 to 2025). A carcinoma that arises from the lung and is characterized by the presence of malignant glandular epithelial cells. "The research findings indicate that ATR, RFC4, and MCM2 are pivotal genes in the pathogenesis of type 2 diabetes and lung adenocarcinoma." (PMID 40282196, 2025). "The analysis results from GEPIA dataset showed that MCM2/4/10 was significantly high expressed in both lung adenocarcinoma (LUAD) and squamous cell lung carcinomas (LUSCs)." (PMID 33936158, 2021). "Immunohistochemical analysis demonstrated the up-regulation of the protein levels of Mcm2, Fen1, Ube2C and cyclin D1 in lung adenocarcinoma tissue of NNK-exposed Gprc5a-knockout mice compared to the levels in normal lung tissue obtained from the same mice." (PMID 20686609, 2010). "MCM2 was considered as a potential therapeutic target for cancer treatment, and the level of MCM2 could predict poor prognosis for osteosarcoma, gastric cancer, lung adenocarcinoma, diffuse large B cell lymphoma, and esophageal cancer." (PMID 32964028, 2020). "Our study found that SH could inhibit Ki-67 and cyclin D1 protein expression in lung adenocarcinoma, promote p21 protein expression, and decrease the MCM2 protein expression levels, thus blocking tumor proliferation and inhibiting A549 cell proliferation activity." (PMID 41444284, 2025). "At the mRNA level, TCGA data indicated that ETV4, MCM2/4/5/10, and ORC1 mRNA levels were all significantly upregulated in 515 lung adenocarcinoma (LUAD) and 503 lung squamous cell carcinoma (LUSC) compared with normal lung tissue." (PMID 40548893, 2025). "The gene expression levels of Ki67, MCM2, CDC20, and CCND3 in tumor tissues from lent-miR-138-5p treated A549 lung adenocarcinoma tumor-bearing mice were lower than those of the other groups." (PMID 32754587, 2020). "In addition, the high expression levels of H2AFX, MCM2, MCM7, and POLD1 correlate with poor prognosis of lung adenocarcinoma (LUAD)." (PMID 33442399, 2021).
melanoma (12 papers, 2013 to 2024). A malignant, usually aggressive tumor composed of atypical, neoplastic melanocytes. "Although the statistical significance was low, we found that high MCM2 expression was associated with poor OS in patients with melanoma, which is consistent with the results of the previous study." (PMID 34490114, 2021). "MCM2 was also found to be associated with lower survival rates, suggesting its possible role as a prognostic predictor in melanoma." (PMID 34490114, 2021). "Similarly, prolonged activity of MCM2 was shown to be associated with vemurafenib resistance in melanoma cells." (PMID 37106808, 2023). "A similar study on BRAFV600E inhibitor-addicted melanoma cells revealed downregulation of MCM2, MCM3 and MCM5 upon drug withdrawal in correlation with reduced cell viability ensuing from discontinued drug treatment." (PMID 37106808, 2023). "Western blotting and CCK-8 assays revealed that MCM2 expression was significantly upregulated in melanoma cell lines." (PMID 35693940, 2022). "To our delight, though the experiment in melanoma cells, we verified that MCM2 promote cell proliferation via regulating the Akt signaling pathway in vitro." (PMID 35693940, 2022). "Very recently, it was found that melanoma is characterized by elevated expressions of MCM-2–6 and MCM-10 proteins." (PMID 34959411, 2021). "Without CDK4/6 inhibitor treatment, in CMM12 cells H2AFZ and MCM2 appeared to be more highly expressed compared to the other melanoma cell lines." (PMID 34485433, 2021). "In our study, the GEPIA showed that the MCM2 mRNA level was much higher in melanoma than in normal skin tissues." (PMID 34490114, 2021). "In summary, we detected elevated expression levels of MCM2–6 and MCM10 in melanoma and found that increased MCM4/5/10 mRNA levels were associated with a worse prognosis for patients with melanoma." (PMID 34490114, 2021). "The bands revealed on blot membranes showed a decreased expression of MCM-2 protein in Mel-Juso cells exposed to γ-Fe2O3 NPs_TPPS followed by irradiation, which confirmed the inhibition of melanoma cells proliferation." (PMID 34959411, 2021). "We observed that H2AFZ and MCM2 were expressed at relatively high levels in CMM12 melanoma cells compared to the other cell lines, suggesting a possible utility of E2F target gene expression in tumor cells as markers to predict response to treatment with a CDK4/6 inhibitor." (PMID 34485433, 2021). "In melanoma cells, a sustained CDC7 expression and associated MCM2–7 activation were observed in vemurafenib-resistant cells, and the CDC7 inhibitor TAK-931 was suggested as a therapeutic option for vemurafenib-resistant melanoma cells." (PMID 33801812, 2021). "We assume that the decrease of MCM-2 protein expression may be a consequence of ROS overproduction induced in melanoma cells through TPPS activation after 1 min irradiation in the presence of γ-Fe2O3 NPs_TPPS." (PMID 34959411, 2021). "Moreover, MCM-2-index is correlated with lower survival rates and this protein in association with COX-2 and p-Akt1 contribute to cell-cycle dysregulation in melanoma." (PMID 34959411, 2021). "Moreover, we showed that photoactivated γ-Fe2O3 NPs_TPPS could trigger apoptosis in melanoma cells and might suppress tumor proliferation and cell adhesion by modulating the MCM-2 and β-catenin pathways." (PMID 34959411, 2021). "We found that the elevated expressions of MCM2–6 and MCM10 were significantly expressed in melanoma compared to normal skin." (PMID 34490114, 2021). "We additionally confirmed the expression with mRNA levels of key genes after treatment with lj-1-59 in melanoma cells, which indicated that P21, BBC3, SESN2 and GADD45A expression were significantly upregulated, while MCM2, MCM3, MCM4, MCM7 and PKMYT1 were significantly downregulated." (PMID 32021565, 2020).
melanoma (continued). "Interestingly, we found that MCM7 was significantly downregulated in MCM2-knockdown groups, indicating the MCM7 may be essential link for MCM2 promoting melanoma cell proliferation." (PMID 35693940, 2022). "As a first step in order to understand if the selected E2F target genes could function as predictor markers of CDK4/6 inhibition resistance, we compared the expression profiles of E2F1, CDC6, DHFR, H2AFZ, MCM2, and ATAD2 among the four canine melanoma cell lines." (PMID 34485433, 2021).
non-small cell lung carcinoma (11 papers, 2006 to 2025). A group of at least three distinct histological types of lung cancer, including non-small cell squamous cell carcinoma, adenocarcinoma, and large cell carcinoma. "IFT57 exerts an oncogenic role in non-small cell lung cancer by activating DNA replication and cell cycle pathways via upregulation of MCM2, MCM6, and MCM8 expression." (PMID 40145017, 2025). "As part of pre-replicative complexes (pre-RCs) that enable G1/S transition, Mcm2–7 are effective prognostic indicators in various kinds of malignancies (e.g., non-small-cell lung cancer)." (PMID 35419294, 2022). "The product (RJ-LC-07-48) is potent against drug-resistant non-small-cell lung cancer (NSCLC) cells by interaction with the minichromosomal maintenance protein MCM2, disrupting the formation of the MCM complex that is required for the initiation of DNA replication." (PMID 37446864, 2023). "MCM2 is an independent predictor of survival in patients with non-small-cell lung cancer." (PMID 32612956, 2020). "Studies have reported that MCM2 is a key molecule involved in the pathogenesis of non-small-cell lung cancer and may be a novel therapeutic target for lovastatin in the treatment of this cancer." (PMID 32420375, 2020). "Although MCM2, Ki-67, two markers of cell proliferation, and gelsolin, marker of cell motility, have been previously studied, no study has been conducted assessing the potential combined prognostic effect of these markers in non-small cell lung cancer (NSCLC)." (PMID 16882345, 2006).
gastric cancer (10 papers, 2014 to 2024). A primary or metastatic malignant neoplasm involving the stomach. "Moreover, MCM2, responsible for DNA synthesis during cell cycle, predicts poor prognosis in gastric cancer." (PMID 33209198, 2020). "Inhibition of MCM2 could suppress the growth of gastric cancer." (PMID 33209198, 2020). "Results in the present study showed that knockdown of AQP-1 decreased protein expression of PCNA and MCM2 in gastric cancer cells, suggesting the anti-proliferative role of AQP-1 silence in gastric cancer." (PMID 33209198, 2020). "Interestingly, four of the identified key genes (CDK6, MCM2, PRKDC, and CCNE1) are on the cell cycle pathway, underscoring the importance of this process in gastric cancer." (PMID 28603669, 2017). "Meanwhile, there have been several articles reveal that MCM2 and MCM5 may serve as prognostic indicators of patients with gastric cancer, but there is no such article on MCM8." (PMID 33155430, 2020). "However, there have been several articles reveal that MCM2 and MCM5 may serve as prognostic indicators of patients with gastric cancer, but there is no such article on MCM8." (PMID 33155430, 2020).
oral squamous cell carcinoma (10 papers, 2005 to 2023). "The expression analysis of cyclin D1, Ki-67, MCM3 and MCM2 in oral squamous cell carcinoma to identify biomarkers is of interest." (PMID 38415027, 2023). "In another study, knockdown of CDC7 in oral squamous cell carcinoma reduced MCM2 and ERK1/2 phosphorylation but promoted Akt phosphorylation." (PMID 31578454, 2019). "The results suggest that cells in oral squamous-cell carcinoma are in a high proliferation state as demonstrated by the high levels of Mcm2, geminin and Ki67." (PMID 19293805, 2009). "Therefore, it is ofinterest to document the expression of cyclin D, Ki-67, MCM3 and MCM2 in oral squamous cell carcinoma to glean biomarkers." (PMID 38415027, 2023). "Mcm2 and geminin have been scarcely explored in oral epithelial dysplasia (OED) and oral squamous-cell carcinoma (OSCC)." (PMID 19293805, 2009).
bladder cancer (9 papers, 2006 to 2024). "MCM2 was demonstrated as a biomarker for esophageal and bladder cancer." (PMID 29463213, 2018). "The prognostic value of MCM2 was also reported in bladder cancer and oligodendroglioma." (PMID 16882345, 2006). "Additionally, the rate of recurrence increases with MCM2 overexpression in bladder cancer." (PMID 34144903, 2022). "Also in a prospective study, detection of MCM2 in voided urinary samples could serve as a promising biomarker for diagnosis of bladder cancers." (PMID 32860339, 2020). "For example, KLF5 binds to a CCNE1 promoter proximal element in bladder cancer cells and KLF5 increases the expression of Ccnb1 and Mcm2 downstream of oncogenic Ras in fibroblasts." (PMID 32880368, 2020).
squamous cell carcinoma (9 papers, 2006 to 2024). A carcinoma arising from squamous epithelial cells. "For MCM2, high expression was associated with sex (male patients: 64.6% vs. 38.8%), histology (squamous carcinomas: 45.6% vs. 6.1%), and grade (poorly differentiated tumors: 68.4% vs. 46.9%)." (PMID 16882345, 2006). "We aimed to investigate proliferation markers ki67, MCM2, and geminin in head and neck cutaneous basal and squamous cell carcinomas." (PMID 32972865, 2022). "The aim of this study was to investigate proliferation markers ki67, MCM2, and geminin in skin basal and squamous cell carcinoma of the head and neck." (PMID 32972865, 2022). "Both MCM2 and SKP2 are implicated in the G1/S phase transition of the mitotic cell cycle and are reported to be co-expressed in lung and squamous cell carcinoma tissue samples, showing the close relationship between these two proteins." (PMID 33339207, 2020). "The mRNA levels of CDC6, CDT1, MCM2 and CDC45 in 31 cases of precancerous epithelial dysplasia and 33 cases of squamous cell carcinoma of the tongue from formalin-fixed, paraffin-embedded specimens were measured using QRT-PCR." (PMID 19116018, 2008).
liver cancer (8 papers, 2018 to 2025). An epithelial or non-epithelial malignant neoplasm that arises from the liver. "The GSEA analysis of TCGA database suggested that MCM2 is associated with stem cells and liver cancer stem cells." (PMID 36243809, 2022). "MCM2 is significantly related to the survival and progression of liver cancer, and its potential mechanism in liver cancer prognosis may involve the cell cycle." (PMID 35463358, 2022). "Thus, inhibitors that target either Hippo signaling or the MCM2 gene may be potential adjuvant therapeutic agents for clinical liver cancer." (PMID 36243809, 2022). "The expression of FEN1 in TCGA liver cancer tissues was positively correlated with that of MCM2 (r = 0.853, P = 0.000), BIRC5 (r = 0.809, P = 0.000), and RFC4 (r = 0.852, P = 0.000), suggesting that FEN1 may play as important a role in the progression of liver cancer as do MCM2, BIRC5, and RFC4." (PMID 31534853, 2019). "When we inhibited CDC7 in liver cancer cells with the CDC7 inhibitor XL413, we observed strong suppression of its downstream target p-MCM2 at XL413 concentrations of 5 μM to 10 μM." (PMID 34663432, 2021). "In the MCM family, abnormal expression of MCM2, MCM3, MCM4, MCM5, and MCM7 also results in reducing prognosis in liver cancer patients according to the HCCDB database." (PMID 32082966, 2019). "Little was previously known about MCM2 and MCM6 protein expression in liver cancer, we observed their up-regulation in HCC." (PMID 29463213, 2018). "As expected, FEN1 expression was significantly positively correlated with that of MCM2, RFC4, and BIRC5 in TCGA liver cancer tissues, suggesting that FEN1 may be as involved in the development of HCC as are MCM2, RFC4, and BIRC5." (PMID 31534853, 2019).
pancreatic cancer (8 papers, 2008 to 2021). "Reduced levels of Mcm2 serine 53 phosphorylation was observed at all PHA-767491 drug concentrations in both pancreatic cancer cell lines and IMR-90 fibroblasts 96 hours following treatment with the inhibitor." (PMID 26921250, 2016). "Recently, it was reported that RRM2, PCNA and MCM2 were downregulated upon treatment with the NSAID NS-398 in pancreatic cancer cells." (PMID 23637916, 2013). "In contrast, in pancreatic cancer, ampullary carcinoma and cholangiocarcinoma, high levels of Mcm2 and -5 expression were seen in all tissue layers indicative of cell-cycle re-entry." (PMID 18414413, 2008). "Furthermore, we have also shown that the expression of Cdc7 strongly correlates with 3 other markers for cell cycle progression (Mcm2, geminin and phosphohistone H3) in pancreatic cancer." (PMID 26921250, 2016). "Overexpression of hsa_circRNA_001587 significantly decreased abilities of pancreatic cancer cell proliferation, migration, invasion, angiogenesis and tumorigenesis through inhibition of oncogenic MMP-2, MMP-9, MCM2, and VEGF expression in pancreatic cancer." (PMID 34439315, 2021). "MCM genes including MCM2, MCM5 and MCM6 were upregulated in pancreatic cancer and show strong positive coexistence with each other." (PMID 33507917, 2021).